IRF4 (interferon regulatory factor 4)
Diseases named in the same sentence as IRF4 in open-access papers (continued):
Sharing a sentence is not in itself a finding about the gene and the disease.
breast carcinoma (10 papers, 2019 to 2026). "In conclusion, our findings highlight the role of JMJD3 in regulating M2-like macrophage polarization and its impact on breast cancer development through the STAT6/IRF4 axis." (PMID 41955245, 2026). "IKZF1 is known to be an important factor in acute lymphoblastic leukemia, IRF4 drives tumor growth in several lymphoid malignancies, and PIK3CG is closely associated with claudin‐low breast cancer migration." (PMID 38506253, 2024). "DEGs Bcl3, ADGRG7, FABP4, IRF4, their regulating miRNAs and TFs have strong impact on proliferation and metastasis of breast cancer in bone tissues." (PMID 35388653, 2022). "MiR-125b also exhibited good anti-tumor effects in murine orthotopic breast cancer, which was attributed to its promotive effect on M1 polarization by targeting interferon regulatory factor 4 (IRF4) in macrophages, and suppressed tumor cells by targeting ETS proto-oncogene 1 and cyclin-J." (PMID 37138859, 2023).
follicular lymphoma (10 papers, 2006 to 2025). Follicular lymphoma is a form of non-Hodgkin lymphoma characterized by a proliferation of B cells whose nodular structure of follicular architecture is preserved. "The mutational profile of the current case closely resembles conventional BCL2‐rearranged low‐grade follicular lymphoma, with the notable exception of the IRF4 mutation." (PMID 39415926, 2024). "The possible oncogenic variants detected in the case of low‐grade follicular lymphoma with interferon regulatory factor‐4 (IRF4)‐R." (PMID 39415926, 2024). "These striking similarities prompt consideration of the potential relationship between low‐grade follicular lymphoma with IRF4 rearrangement and LBCL‐IRF4‐R." (PMID 39415926, 2024). "This underscores the need for further investigation into similar cases to further explore the relationship between low‐grade follicular lymphoma or other small B‐cell lymphomas with IRF4 rearrangement and LBCL‐IRF4‐R." (PMID 39415926, 2024). "We present a case of classic low‐grade follicular lymphoma with IRF4 rearrangement in a 50‐year‐old male, demonstrating an unusual immunophenotypic and genetic profile reminiscent of LBCL‐IRF4‐R." (PMID 39415926, 2024). "The differential diagnosis of LBCL, IRF4+ includes first pediatric‐type follicular lymphoma (PTFL), which also affects children and adolescence predominantly, and present similarly with a follicular lymphoid proliferation composed of large neoplastic cells." (PMID 37081786, 2023). "Conventional follicular lymphoma, Grade 3B (FL3B), or follicular LBCL, needs to be distinguished from LBCL, IRF4+, too, due to the similar morphological findings and a frequent IRF4/MUM1‐positive phenotype, but conventional FL3B occurs more commonly in adults, and lacks the IRF4 translocation." (PMID 37081786, 2023).
renal fibrosis (10 papers, 2019 to 2025). A final common manifestation of a wide variety of chronic kidney diseases characterized by glomerulosclerosis and tubulointerstitial fibrosis. "The JMJD3-interferon regulatory factor 4 (IRF4) axis has been implicated in renal fibrosis progression." (PMID 40042761, 2025). "Deteriorated alternative macrophage subpopulations in Irf4−/− mice provoke chronic intrarenal inflammation, tubular epithelial cell loss, and renal fibrosis in the long course after IRI in mice." (PMID 31632388, 2019). "Furthermore, IRF4 deficiency reduces inflammation and renal fibrosis following acute kidney injury induced by folic acid." (PMID 38195465, 2024). "IRF4-deficient mice exhibited defects in macrophage polarization, leading to the infiltration of macrophages and the release of pro-inflammatory cytokines by macrophages, subsequently causing intrarenal chronic inflammation and renal fibrosis." (PMID 37508555, 2023). "Furthermore, our data clearly contradict the concept that a Th1 > Th2 primed adaptive immune response can per se be considered protective, as IRF4-deficient mice showed a clear Th1 signature yet developed massive renal fibrosis following AKI." (PMID 31632388, 2019). "Moreover, α-SMA and Sirius red staining revealed increased renal fibrosis 5 weeks after IRI in IRF4-deficient animals compared with C57BL6 WT mice." (PMID 31632388, 2019). "Taken together, we demonstrate that Jmjd3/IRF4 axis plays a crucial role in bone marrow fibroblasts differentiation and renal fibrosis progression." (PMID 36159833, 2022). "Our data reveal that IRF4 suppresses the progression to renal fibrosis and CKD 3–5 weeks following IRI in mice, which is the essential end point for those recovering from acute renal failure." (PMID 31632388, 2019). "We next examined the effect of genetic ablation of IRF4 on renal fibrosis induced by UUO injury." (PMID 36159833, 2022). "have reported that myeloid IRF4 deletion attenuates ischemia-induced renal fibrosis." (PMID 36159833, 2022). "To further understand the signaling pathway mechanism of Jmjd3 in kidney fibrosis, we investigate whether IRF4 mediates the anti-fibrotic effects of Jmjd3 inhibition in renal fibrosis." (PMID 36159833, 2022). "In addition to reduced kidney injury, macrophage IRF4–/– animals demonstrated decreased renal fibrosis at both the transcript and protein levels 4 weeks following AA treatment." (PMID 35025763, 2022). "Herein, we aimed to test the following hypotheses: First, we hypothesized that IRF4, in addition to its acute anti-inflammatory role, limits the chronic inflammatory response, residual renal damage, and renal fibrosis." (PMID 31632388, 2019). "Targeting Jmjd3/IRF4 signaling may be a promising therapeutic strategy in renal fibrosis." (PMID 36159833, 2022). "There are also relevant studies the Jmjd3/IRF4 signalling pathway is crucial for activating bone marrow fibroblasts, promoting MMT, depositing extracellular matrix proteins, and advancing renal fibrosis." (PMID 39445007, 2024). "The remaining signalling pathways mediating renal fibrosis are STING/TBK1, IL-4Ra/STAT6, Jmjd3/IRF4, STAT6/PPARα, SETD7, NKT/IL-4, BRP-39, STAT-1/TREM-1, MMP-9/Akt, adiponectin/APK, and JAK3/STAT6." (PMID 39445007, 2024). "We show that Jmjd3 depletion in myeloid cells (Jmjd3flox/flox Lyz2Cre+) or IRF4 disruption impairs myeloid fibroblasts activation, inhibits M2MMT, and attenuates renal fibrosis progression." (PMID 36159833, 2022). "The authors of a previous study reported that the absence of IRF4 can reduce renal fibrosis after acute renal injury by reducing the recruitment and activation of macrophages." (PMID 39609883, 2024). "IRF4-/- reduces folate AKI induced inflammation and renal fibrosis." (PMID 37063876, 2023).
rheumatoid arthritis (10 papers, 2017 to 2023). A chronic, systemic autoimmune disorder characterized by inflammation in the synovial membranes and articular surfaces. "IRF4 dysregulation has been described in rheumatoid arthritis and SLE and it is associated with initiation and disease progression." (PMID 34944673, 2021). "More recent findings suggest that IRF4 polymorphisms are associated with high risk of rheumatoid arthritis (RA) and systemic sclerosis." (PMID 30515152, 2018). "Additionally, B. longum RAPO significantly inhibited Th17 cells and Th17-related genes—IL-17A, IRF4, RORC, IL-21, and IL-23R—in the PBMCs of rheumatoid arthritis patients." (PMID 34867956, 2021).
Arthritis (9 papers, 2013 to 2024). Inflammation of a joint. "In support of the importance of IRF4, there is recent evidence that IRF4, most likely acting in monocytes/macrophages, is important in controlling how GM-CSF promotes arthritis and associated pain, as well as inflammatory pain per se." (PMID 31552022, 2019). "We have also reported that both GM-CSF-driven inflammatory pain and arthritis models (using exogenous GM-CSF), and GM-CSF-dependent inflammatory pain and arthritis models (e.g. zymosan-induced arthritis (ZIA)) are dependent on IRF4 and CCL17, and on TNF." (PMID 29622035, 2018). "Results from GSE36700 containing synovial tissue samples from 5 OA, 4 SLE, 5 microcrystalline arthritis (MA) and 7 RA patients confirmed the differential expression of IRF4 (adjusted p = 8.4·10−4), again being upregulated in RA." (PMID 30666255, 2018). "While Tnf−/− and WT mice had comparable scores, both Irf4−/− and Ccl17E/E mice had less arthritis compared to WT mice, with the mean score significantly lower for both strains compared to that observed in WT mice." (PMID 29622035, 2018). "Interestingly, the GFP-modified Foxp3 was protective in a model of arthritis due to disruption in HIF1α binding and increasing Foxp3 interactions with Interferon Regulatory Factor 4 (IRF4) leading to improved Treg control of Th2 and Th17 responses." (PMID 36032083, 2022). "For example, altered IRF4 function may explain the difference between the T helper 1 (Th1) cell-mediated disease in the diabetes model and the Th2-dependent arthritis model." (PMID 23593464, 2013). "In murine models of arthritis, GM‐CSF up‐regulated IRF4 and thus CCL17 production by enhancing the expression of the epigenetic enzyme JMJD3 demethylase, which activates IRF4 expression." (PMID 29315512, 2018).
anaplastic large cell lymphoma (8 papers, 2018 to 2024). Anaplastic large cell lymphoma (ALCL) is a rare and aggressive peripheral T-cell non-Hodgkin lymphoma, belonging to the group of CD30-positive lymphoproliferative disorders, which affects lymph nodes and extranodal sites. "Moreover, rarer sub-entities such as MYC and BCL2 “double hit lymphomas” (DHL), IRF4-rearranged large cell lymphoma (IRF4-LCL), and Burkitt-like lymphomas with 11q aberration pattern (mnBLL-11q) attracted interest while their relatedness regarding the major classes is still unclear in many respects." (PMID 35884496, 2022).
colon cancer (8 papers, 2021 to 2024). "The methylation and expression level of IRF4 have been reported to be associated with the development of colon cancer." (PMID 39030645, 2024). "As a tumour suppressor, RNF2 E3 ligase promotes proliferation of colon cancer cells by increasing IRF4 degradation through K48‐linked ubiquitination." (PMID 37341064, 2023). "Previous study has confirmed that 8 tag single nucleotide polymorphism in IRF4 are associated with colon cancer." (PMID 33468159, 2021). "However, IRF4 silencing caused an increase in the proportions of Tregs and M2 macrophages, and repressed the proportions of M1 macrophages in colon cancer tissues." (PMID 33468159, 2021). "Therefore, down-regulation of IRF4 may be associated with the polarization of Tregs in colon cancer." (PMID 33468159, 2021). "To explore the biological role of IRF4 in colon cancer, we overexpressed or knocked down IRF4 in SW480 cells by transfecting them with LV-IRF4 or LV-sh-IRF4." (PMID 33468159, 2021). "The data obtained from qRT-PCR and WB showed that IRF4 was highly expressed in colon cancer tissues with respect to the normal paracancerous colon tissues." (PMID 33468159, 2021). "MYC, LEF1, KLF4, SALL4, and IRF4 were the five important TFs involved in the regulation of the immune response in colon cancer." (PMID 34938284, 2021). "In conclusion, our data demonstrated that IRF4 overexpression promoted the transdifferentiation of Tregs into macrophage-like cells to inhibit the occurrence and development of colon cancer." (PMID 33468159, 2021). "Taken together, our findings showed that exosomes derived from colon cancer cells down-regulated IRF4 expression in Tregs by transmitting miRNAs." (PMID 33468159, 2021). "Exosomes derived from colon cancer cells repressed IRF4 expression in Tregs by transmitting miR-27a-3p, miR-30a-5p and miR-320c." (PMID 33468159, 2021). "IRF4 overexpression promoted the transdifferentiation of Tregs into macrophage-like cells to inhibit the occurrence and development of colon cancer." (PMID 33468159, 2021). "Taken together, these data demonstrated that IRF4 overexpression inhibited colon cancer by promoting the transdifferentiation of Tregs into macrophage-like cells." (PMID 33468159, 2021). "We compared the expression of IRF4, the number of regulatory T cells (Tregs) and macrophages in the colon cancer tissues and paracancerous colon tissues from colon cancer patients." (PMID 33468159, 2021). "To disclose differentially expressed IRF4 in colon cancer, we analyzed IRF4 expression in colon cancer tissues and paracancerous colon tissues from colon cancer patients." (PMID 33468159, 2021). "Taken together, these data suggested that exosomes derived from colon cancer cells down-regulated IRF4 expression in Tregs by transmitting miRNAs." (PMID 33468159, 2021). "We found that IRF4 was severely down-regulated in the colon cancer tissues." (PMID 33468159, 2021). "We wondered whether colon cancer cells can inhibit the expression of IRF4 in Tregs through secreting exosomes." (PMID 33468159, 2021). "The colon cancer tissue damage was attenuated in LV-IRF4 group and aggravated in LV-sh-IRF4 group." (PMID 33468159, 2021). "Furthermore, the mechanism of action of IRF4 in transdifferentiation of Tregs into macrophage-like cells and the effect of IRF4 on colon cancer cells were investigated in vitro." (PMID 33468159, 2021). "Moreover, IRF4 up-regulation ameliorated tumor growth of colon cancer by promoting the transdifferentiation of Tregs into macrophage-like cells through inhibition of BCL6 expression." (PMID 33468159, 2021). "Moreover, IRF4 overexpression reduced the proportions of Tregs and M2 macrophages, and enhanced the proportions of M1 macrophages in colon cancer tissues of mice." (PMID 33468159, 2021). "Furthermore, IRF4 overexpression repressed proliferation, migration and invasion of colon cancer cells (SW480 and HT116 cells)." (PMID 33468159, 2021).
colon cancer (continued). "Our data first revealed the biological role of IRF4 in colon cancer." (PMID 33468159, 2021). "IRF4 was severely down-regulated in the colon cancer tissues." (PMID 33468159, 2021). "Thus, we suggested that IRF4 overexpression inhibited colon cancer progression by promoting the transdifferentiation of Tregs into M1 macrophages." (PMID 33468159, 2021). "The aim of this study is to investigate whether IRF4 participates in the immune response in colon cancer." (PMID 33468159, 2021). "Next, we explored whether IRF4 participated in the transdifferentiation of Tregs in colon cancer." (PMID 33468159, 2021). "Thus, IRF4 overexpression had an inhibiting effect on the progression of colon cancer." (PMID 33468159, 2021). "However, the biological role of IRF4 in colon cancer is still unclear." (PMID 33468159, 2021). "Thus, IRF4 may be a potential target for colon cancer treatment." (PMID 33468159, 2021). "This study determined that IRF4 and TNFRSF17 were immune-related genes in colon cancer, providing immune-related prognostic biomarkers for colon cancer." (PMID 34900677, 2021). "Our in vivo assays further revealed that the inoculation of IRF4-overexpressed SW480 cells effectively attenuated the colon cancer tissue damage, whereas IRF4 knockdown aggravated the colon cancer tissue damage in colon cancer mouse model." (PMID 33468159, 2021). "Additionally, Wang Team demonstrated that IRF4 exerts a negative regulatory effect on BCL6, facilitating Treg cell differentiation into macrophage-like cells and consequently impeding colon cancer cell proliferation." (PMID 39582536, 2024).
Hodgkins lymphoma (8 papers, 2013 to 2025). A heterogeneous group of malignant lymphoid neoplasms of B-cell origin characterized histologically by the presence of Hodgkin and Reed-Sternberg (HRS) cells in the vast majority of cases. "If so this would be predicted to pertain as the predominant mode of IRF4 occupancy in EBV-driven B-cell malignancies, such as EBV-associated DLBCL and EBV-associated classical Hodgkin lymphoma." (PMID 24875472, 2014). "Recent reports suggested that siRNA mediated IRF4 knockdown inhibits Hodgkin Lymphoma cell proliferation and survival." (PMID 23658517, 2013). "This analysis highlighted that many KEGG Hodgkin lymphoma pathway genes are jointly induced by TES1 and TES2 signaling in LCLs, including CCL22, BCL3, cRel, IRF4, STAT3, STAT6, and CD70, each of which has prominent roles in Hodgkin lymphoma pathogenesis." (PMID 38009935, 2023). "IRF4 is one of the TLS-related genes 23, and it is widely regarded as a cancer-promoting gene in numerous tumors, including lung cancer, cholangiocarcinoma, and Hodgkin lymphoma 52,81,82." (PMID 40607252, 2025).
inflammatory bowel disease (8 papers, 2012 to 2025). A spectrum of small and large bowel inflammatory diseases of unknown etiology. "IRF4 is broadly expressed in immune system cells and has been linked to conditions such as asthma, inflammatory bowel disease, and autoimmune diseases." (PMID 38195465, 2024). "On the other hand, IRF4 is also thought to control ROR-γt-dependent Th17 inflammatory bowel disease by regulating il17a promoter activity." (PMID 33803441, 2021). "Another observation is that all four genome-wide significant risk loci (PLA2R1, IRF4, NFKB1, and HLA) exhibit highly pleiotropic effects and all four lead SNPs have a concordant effect on the risk of inflammatory bowel disease (IBD)." (PMID 32231244, 2020). "IRF4 is involved in the pathological process of a variety of inflammatory diseases, including the promotion of interleukin(IL)-6 production in inflammatory bowel disease, which induces STAT3 expression in T lymphocytes to promote apoptosis followed by intestinal inflammation." (PMID 38195465, 2024). "In 5-Tm, GOs including Th17 differentiation pathway, inflammatory bowel disease, and allograft rejection, represented by IL12RB1, IRF4, LAT, and IL22, were observed in PE." (PMID 38774869, 2024).
acute myeloid leukemia (7 papers, 2009 to 2025). Acute myeloid leukemia (AML) is a group of neoplasms arising from precursor cells committed to the myeloid cell-line differentiation. "Concurrently, a plethora of research has highlighted a consistent downregulation of IRF4 expression across the myeloid disease spectrum, encompassing acute myeloid leukemia (AML), chronic myeloid leukemia (CML), and a range of hematopoietic cancer cell lines." (PMID 40073065, 2025). "MIR223HG, acting as a competing endogenous RNA, inhibited acute myeloid leukemia progression by inducing IRF4 expression." (PMID 38914679, 2024).
allergic disease (7 papers, 2012 to 2022). An immune response that occurs following re-exposure to an innocuous antigen, and that requires the presence of existing antibodies against that antigen. "Perhaps most importantly, our data shows an important role for FoxO1 in macrophages in the contribution of allergic disease, and highlight the separate role that FoxO1 could be a major inducer of IRF4 in macrophages, through gain and loss-of-function studies." (PMID 27007158, 2016). "The literature clearly supports a key role for IRF4-dependent cDC2s in allergy and humoral responses, yet a regulatory role is evident under certain conditions." (PMID 30531969, 2018). "Th9 cells, a new member of CD4+ T cell family which is characterized by its specific cytokine IL-9 and transcription factors PU.1 and IRF-4, have been known recently to have a critical role in allergic diseases, and cancers as well as the parasitic infection." (PMID 26509179, 2015). "Indeed, the adjuvant CT, orally fed to mice, generates allergy in vivo by inducing upregulation of DC genes that prime for Th2 responses, such as Irf4, Tnfsf4, and Jagged2, in the PPs and MLNs." (PMID 34684302, 2021). "We recently described increased NFATc1, IRF4, and NIP45 messenger RNA (mRNA) expression in peripheral blood mononuclear cells (PBMCs) of asthmatic children and adults with multiple allergies." (PMID 33079489, 2020).